TPO (thyroid peroxidase)
Diseases named in the same sentence as TPO in open-access papers (continued):
Sharing a sentence is not in itself a finding about the gene and the disease.
Autoimmunity (continued). "Our recent study has demonstrated more intensive thyrocyte lysis in the presence of IgG isolated from HT patients than from healthy donors, which resulted from the higher anti‐TPO content in the whole IgG pool of HT donors and the altered IgG N-glycosylation in HT autoimmunity." (PMID 35370997, 2022). "As a result of autoimmunity to self-antigens, approximately 60%–80% of patients with HT have serum antibodies against thyroglobulin (Tg) and 90%–95% have antibodies against thyroid peroxidase (TPO)." (PMID 33746952, 2021). "The amino acid changes in the region may change the three-dimensional structure, which could impact the catalytic activity or the autoimmunity of TPO." (PMID 34209805, 2021). "Neither neonatal TSH nor maternal TPO-positivity was different between the intervention and the control groups despite the known association between iodine and autoimmunity." (PMID 33620551, 2021). "Evidence for autoimmunity (positive anti-thyroid peroxidase antibodies, anti-nuclear antibodies or autologous serum test) was found in 45.2% (n = 19/42), and high C-reactive protein was present in 14.3% (n = 6/42), half of these also had positive antinuclear antibodies." (PMID 33292453, 2020). "Thus, anti-TPO levels cannot be considered a differential diagnostic marker between GD and TMNG; rather, they can be considered a marker of autoimmunity." (PMID 32631402, 2020). "This could be explained by the fact that anti TPO antibody is an early marker of autoimmunity so it appears before the development of functional thyroid dysfunction." (PMID 32968394, 2020). "In another study premature ovarian failure (POF) was significantly associated with adrenal cortex autoantibodies, which may be due to general autoimmunity that affects multiple organs and TPO Ab is a part of this process that has destructive effect on oocytes." (PMID 31064360, 2019). "High anti-TPO and anti-Tg levels indicate the presence of autoimmunity against the thyroid." (PMID 30532779, 2018). "Also, highIgE-anti-TPO is correlated with increased lymphocyte counts and C4 consumption, twocommon features of autoimmune conditions." (PMID 21532759, 2011). "This hormonal regulation is considered important for the suppression of autoimmunity during hormonally induced changes in thyroid cell function, which results in an enhanced expression of potential thyroid autoantigens, such as thyroglobulin, thyroid peroxidase, and the TSH receptor." (PMID 34938270, 2021). "Anti-TPO and anti-Scl-70 remained elevated at high levels in all seropositive subjects regardless of the time of measurement, suggesting that these autoantibodies were already present at hospitalization and likely represent preclinical (asymptomatic), unreported, or undiagnosed autoimmunity." (PMID 34521836, 2021). "AITDs are multifactorial diseases in which autoimmunity plays a fundamental role with infiltration of the gland by T- and B-cells and production of specific autoantibodies, reactive to thyroid antigens [antithyroglobulin, anti-thyroid peroxidase (TPOAb), and anti-TSH receptor (TRAb)]." (PMID 26681939, 2015). "Anti-TPO and anti-tissue antibodies were more frequently detected in T1DM, suggesting broader autoimmunity." (PMID 41008668, 2025). "For measures of autoimmunity, we evaluated antinuclear, antineutrophil cytoplasmic (ANCA), rheumatoid factor, double stranded DNA, antithyroglobulin, and thyroid peroxidase antibodies." (PMID 40776635, 2025). "To investigate further, we measured anti-TPO levels as well as levels of anti-nuclear antibodies (ANA), a more general biomarker of autoimmunity." (PMID 38946973, 2024). "Eventually, cross-reactivity between TPO and MPO may be another mechanism involved in the development of autoimmunity, due to the strong homology between amino acids 586–601 of TPO and amino acids 594–609 of MPO." (PMID 28626447, 2017). "However, screening for autoimmunity with measurement of anti-TPO ab titer is currently not done regularly." (PMID 35165548, 2022).
Autoimmunity (continued). "Anti-TPO antibody, which is a better marker than TM-Ab of autoimmunity, was not assessed." (PMID 24282581, 2013). "In men, the presence of anti-thyroid peroxidase antibodies (anti-TPO) leads to lower SHBG concentration, nevertheless, this correlation is not an independent predictor of autoimmunity." (PMID 40427034, 2025). "However, when evaluating for differences within the DS cohort based on various metrics of autoimmunity, we did not observe important differences based on number of autoimmune/inflammatory conditions, ANA or TPO positivity status, or number of other autoantibodies." (PMID 38946973, 2024).
hyperthyroidism (85 papers, 2010 to 2026). Overactivity of the thyroid gland resulting in overproduction of thyroid hormone and increased metabolic rate. "Carbimazole and propylthiouracil, two inhibitors of thyroid peroxidase (encoded by TPO) used in hyperthyroidism, were also predicted to target littoral cells, as well as spleen_art_ec." (PMID 39566559, 2024). ",46TPO encodes the thyroid peroxidase protein, which is the target of several approved drugs for the treatment of hyperthyroidism." (PMID 37433298, 2023). "TPO is an enzyme essential for thyroid gland function involved in T4 and T3 production, and mutations in this gene can lead to hyperthyroidism." (PMID 33382739, 2020). "Compared with the reference group (euthyroidism and TPO Ab−), subjects with subclinical hyperthyroidism and TPO Ab+/− had a higher risk of LBW in multivariate analyses (OR: 1.94, 95% CI: 1.06, 3.55), but not in univariate analyses." (PMID 33613448, 2020). "Positivity for anti-TPO antibodies was a risk factor for developing radioiodine-induced hyperthyroidism in this study also." (PMID 29069397, 2018). "The first two mechanisms mentioned could be related to hyperthyroidism propension because TAS2R agonists such as propylthiouracil, approved for hyperthyroidism treatment, can inhibit TPO and type 1 deiodinase activity." (PMID 37432370, 2023). "The identified variants are therefore expected to be a mix of variants, which have been previously associated with hypo or hyperthyroidism (e.g., TPO, FOXE1, and ATXN2) and variants that lead to a TSH level, which is slightly above or below the population-based reference ranges." (PMID 30367059, 2018). "Methimazole (MMI) is a pharmaceutical specifically designed to treat hyperthyroidism by inhibiting thyroperoxidase (TPO), while the herbicide amitrole has unintentional TPO-inhibiting properties." (PMID 42205262, 2026). "Assessing for TRAb/TSI in addition to TPO Ab can be useful in ICI-induced hyperthyroidism if GD is suspected." (PMID 39701285, 2025). "There was no statistical significance in the detection rates of clinical hyperthyroidism, subclinical hypothyroidism, subclinical hypothyroidism, goiter, thyroid nodules, TPO Ab and TG Ab positive rates in different iodine nutritional status (P>0.05)." (PMID 37745704, 2023). "Vice versa, methimazole, a TPO inhibitor used in the clinic to treat hyperthyroidism, also potently inhibits collagen IV cross-link formation by PXDN." (PMID 38275643, 2023). "Known risk factors for post-RAI GD include preexisting subclinical hyperthyroidism, positive thyroid peroxidase autoantibodies (TPOAb), positive TSH receptor autoantibodies (TRAb) or otherwise undiagnosed GD." (PMID 39354980, 2022). "Six months later the patient accepted a GFD and was observed to have a persistent increase in TPO-Ab and Tg-Ab with subclinical hyperthyroidism development." (PMID 35458242, 2022). "During the study period, out of 1701 patients who received activity of RAI between 148 and 555 MBq, 152 patients with Graves’ hyperthyroidism and a known TPO Ab status were included." (PMID 35687484, 2022). "The appearance of other antibodies against thyroid antigens such as anti-Tg and anti-TPO antibodies was reported in patients with hyperthyroidism." (PMID 34033291, 2021). "Investigations revealed adrenal insufficiency and subclinical hyperthyroidism with elevated anti-thyroid peroxidase antibodies." (PMID 32455083, 2020). "But it cannot explain the full picture of our results, such as TPO-abs being related positively to hyperthyroidism, and so seems an implausible explanation for all of our findings." (PMID 31791284, 2019). "Following blood biochemistry, muscle enzyme and thyroid function tests, 1 patient had hyperthyroidism with positive thyroglobulin and anti-thyroid peroxidase antibodies." (PMID 25780436, 2015).
hyperthyroidism (continued). "The duration of hyperthyroidism in these cases was reported to range from 1 to 23 months and to be positively correlated with thyroid peroxidase autoantibody levels at presentation." (PMID 25541900, 2014). "She had been diagnosed with amiodarone-induced hyperthyroidism, although she had showed repeated high titers of anti-TPO." (PMID 21941581, 2012). "A recent case in 2022 described a 29-year-old woman who presented with a painful and pruritic rash with signs and symptoms of hyperthyroidism including biochemical evidence of hyperthyroidism with positive TPO antibodies, positive TSH receptor antibodies and low complement C3 levels." (PMID 37251685, 2023). "Prior to the treatment with 177Lu-DOTATATE, the patient had primary hyperthyroidism, and the presence of elevated anti-TPO and anti-Tg antibodies and an undetectable TrAb, suggested that the patient was likely in the thyrotoxicosis phase of Hashimoto’s (autoimmune) thyroiditis." (PMID 33551992, 2020). "Similarly, 93/118 (78.8%) subjects in group A2 had either anti-TPO or anti-Tg prior to the onset of subclinical/overt hyperthyroidism compared to 81/118 (68.6%, p= 0.1033) with anti-TPO and 58/118 (49.2%, p<0.0001) with anti-Tg." (PMID 31467701, 2019). "The incidence of anti-TPO positivity seen earlier than the onset of subclinical/overt hyperthyroidism was significantly higher (p<0.0001) than the combined control group and the anti-TPO was positive in an average of 277 (±151) days ahead of the onset of subclinical/overt hyperthyroidism." (PMID 31467701, 2019). "However, other factors could have interfered since, for example, previous episodes of hyperthyroidism were more frequent in the TPO Ab-positive group, which could have elicited immunization against thyroid antigens, including TPO." (PMID 35687484, 2022). "In the present study, compared with Thy-Tet1+/+ mice, Thy-Tet1−/− mice developed hyperthyroidism, accompanied by elevated levels of PAX8, TPO and NIS." (PMID 41152554, 2025). "Firstly, the discovery of a homologous 11-residue peptide shared by both gastric parietal cell antigens and thyroid peroxidase suggests a common epitope, implying that antibodies generated during H. pylori infection may cross-react with thyroid antigens, potentially contributing to hyperthyroidism." (PMID 39963276, 2025). "SCH, thyroid peroxidase antibody, isolated hypothyroxinemia, subclinical hyperthyroidism, and depression during pregnancy was not identified as a risk factor for IUGR." (PMID 40585911, 2025). "Anti-TPO and anti-TG antibodies are related to levels of thyroid-stimulating hormone (TSH) and both alone or in combination have been used to predict the development of hypo-/hyperthyroidism." (PMID 37821852, 2023). "Also overrepresented within cluster 2 are cases positive for anti–thyroid peroxidase (TPO)/thyroglobulin (TG) antibodies and Grave’s hyperthyroidism." (PMID 37379383, 2023). "Compared to patients with a negative TPO Ab status, patients with a positive TPO Ab status are younger, had more previous episodes of hyperthyroidism, have a higher thyroid gland volume, and more frequently received ATD before administration of RAI." (PMID 35687484, 2022). "Compared to TPO Ab-negative patients, TPO Ab-positive patients were younger, had a larger thyroid gland, and had more previous episodes of hyperthyroidism." (PMID 35687484, 2022). "These variables were analysed in the hypo and hyperthyroid phase: age, sex, initial TSH, free triiodothyronine (fT3), free thyroxine (fT4), anti-TPO, TBII antibodies, parietal cell autoantibodies, time between hypo and hyperthyroidism, thyroid volume and levothyroxine doses (LT)." (PMID 30624501, 2018). "These authors studied whether there was a correlation between the dose of treatment with levothyroxine and the levels of anti-TPO antibodies with the development of TBII antibodies and subsequent hyperthyroidism." (PMID 30624501, 2018).
hyperthyroidism (continued). "It is characterized by hyperthyroidism and specific thyroid autoantibodies against thyroid-stimulating hormone receptor (TSHR) and is also commonly accompanied by autoantibodies against thyroglobulin (TG) and thyroid peroxidase (TPO)." (PMID 29259988, 2017). "Only two (7.1%) of the anti-TPO Ab positive participants and one (1.4%) of the negative participants had hyperthyroidism." (PMID 25653881, 2015). "In patients with GH, decrease in serum TPO and Tg antibody titres correlated with both a fall in TSHr antibody levels, when measured (results not shown), and improvement in hyperthyroidism, manifested by need for reducing doses of antithyroid medication." (PMID 26798548, 2015). "Due to financial constraints, genetic testing of the parents could not be performed; however, both parents were clinically and biochemically euthyroid and tested negative for anti-thyroid peroxidase antibodies, making a familial form of nonautoimmune congenital hyperthyroidism unlikely." (PMID 41018437, 2025). "However, the patient had hyperthyroidism with anti-TPO antibody and anti TSH receptor antibody positive, which suggest that the hyperthyroidism did not develop simply because of the transfer of adoptive immunity." (PMID 26777050, 2015).
thyroid cancer (78 papers, 2001 to 2026). "Patients with CH due to TPO gene mutations are subject to a higher risk of developing thyroid cancer than other populations." (PMID 40665986, 2025). "Among people undergoing thyroidectomy for any reason, thyroid cancer risk was also associated with the presence of anti-Tg antibodies, though the evidence was mixed regarding anti-thyroid peroxidase (TPO) seropositive status." (PMID 35380164, 2022). "Overexpression of the Notch signaling pathway, including that of Notch1, Notch3, and Hes1, is directly associated with a differentiation phenotype (NIS, TPO) expression of both thyroid cancers and TSH-stimulated normal thyroid cells." (PMID 33995657, 2021). "The association between TPO gene mutations including intronic variants and missense variants and thyroid carcinoma was also seen in humans." (PMID 34209805, 2021). "There are a small number of previously reported cases of thyroid carcinoma in TPO gene mutation patients who harbored multinodular goiter." (PMID 26761947, 2016). "Additionally, TPO (thyroid peroxidase) gene, which plays a key role in thyroid hormone synthesis, have been reported to be associated with thyroid carcinoma and thyroid autoimmune response." (PMID 37600696, 2023). "Many TPO isoforms were detected in breast cancer samples and an increased proportion of TPO alternatively-spliced mRNA variants can be observed in various types of thyroid cancer." (PMID 28575127, 2017). "Therefore, long-term follow-up of patients with TPO gene mutations is warranted also for early detection of thyroid carcinoma arising in multinodular goiter." (PMID 26761947, 2016). "To better understand the role of TPO in the development of thyroid cancer, we applied GSEA to analyze the signatures of TPO." (PMID 37407700, 2023). "We analyzed data from the TCGA database to compare the expression levels of TPO between thyroid cancer and normal thyroid tissue." (PMID 37407700, 2023). "A model based on histological subtype, TPO and NIS expression and TERT promoter mutation, all evaluated on initial surgical material, can predict iodine avidity in thyroid cancer tissue ahead of treatment." (PMID 37352166, 2023). "Thyroid peroxidase (TPO) is responsible for the effective organification and retention of iodine tracers in thyroid cancer cells and in the normal thyroid." (PMID 36012698, 2022). "The present review systematically evaluated the possible association between human exposure to selected compounds inhibiting thyroid hormone synthesis via inhibition of the TPO and thyroid cancer incidence and mortality." (PMID 33492873, 2022). "Univariate analysis showed that sex, age, history of radiation, family history, thyroid cancer, autoantibodies to thyroid peroxidase, thyroid-stimulating hormone level, and nodule size were associated with suspicious thyroid nodules." (PMID 33503181, 2021). "We have previously reported that both TG and TPO mRNA and protein are re-expressed in dedifferentiated thyroid cancer cells (NKX2-1−/PAX8+) infected with adenoviral vectors containing Nkx2-1 (AdNKX2-1), which induces radioiodide organification and retention." (PMID 34748583, 2021). "Thyroid-specific genes, including thyroid-stimulating hormone receptor (TSHR), sodium/iodide symporter (NIS), thyroperoxidase (TPO) and thyroglobulin (TG), are downregulated in thyroid cancer." (PMID 34155535, 2021). "This case illustrates that TPO cfRNA can be a potential tool to detect recurrent or persistent thyroid cancer, and its level can fall within a day after treatment, indicating that measurements are instant snapshots of the molecular physiology in time." (PMID 34512731, 2021). "In thyroid cancer, thyroid peroxidase (TPO) activity, and thus organification of free iodide is reduced." (PMID 30902086, 2019). "The expression levels of CHEK1, c-KIT, SLC26A4, TG and TPO were significantly altered in all types of thyroid carcinomas." (PMID 27329729, 2016).